AP1S1 (adaptor related protein complex 1 subunit sigma 1)
Description:
Subunit of clathrin-associated adaptor protein complex 1 that plays a role in protein sorting in the late-Golgi/trans-Golgi network (TGN) and/or endosomes. The AP complexes mediate both the recruitment of clathrin to membranes and the recognition of sorting signals within the cytosolic tails of transmembrane cargo molecules.
Synonyms: AP19; CLAPS1; SIGMA1A; WUGSC:H_DJ0747G18.2; EKV3; MEDNIK
Tractability: Antibody: UniProt places it where antibodies can reach, with high confidence. PROTAC: ubiquitination databases record sites on it; its protein half-life has been measured.
Gene: Protein-coding gene on chromosome 7 (101,154,352 to 101,161,596, forward strand). Ensembl gene ENSG00000106367.
Subcellular location: Golgi apparatus; Cytoplasmic vesicle membrane; Membrane, clathrin-coated pit
Subcellular location (Human Protein Atlas): Golgi apparatus; Vesicles
Pathways (Reactome):
Vesicle-mediated transport: Golgi Associated Vesicle Biogenesis; Lysosome Vesicle Biogenesis
Disease: Nef mediated downregulation of MHC class I complex cell surface expression
Immune System: MHC class II antigen presentation
Gene Ontology:
Molecular function: clathrin adaptor activity
Biological process: response to virus; basolateral protein secretion; melanosome assembly; platelet dense granule organization; receptor-mediated endocytosis; vesicle-mediated transport; intracellular protein transport; protein transport
Cellular component: Golgi apparatus; membrane; AP-1 adaptor complex; cytoplasmic vesicle membrane; cytosol; early endosome; Golgi membrane; lysosomal membrane; trans-Golgi network membrane; clathrin-coated pit; membrane coat; presynapse; terminal bouton
Genetic constraint (gnomAD): Loss-of-function variants: 13 observed, 19.16 expected, observed/expected ratio (o/e) 0.68, 90% interval 0.44 to 1.08. The upper end of that interval is the gene's LOEUF score, 1.08, which puts it in group 4 of 6, group 1 being the genes least tolerant of losing a copy. Missense variants: 119 observed, 183.15 expected, observed/expected ratio (o/e) 0.65, 90% interval 0.56 to 0.76. Synonymous variants: 84 observed, 73.02 expected, observed/expected ratio (o/e) 1.15, 90% interval 0.96 to 1.38.
Gene-disease validity (ClinGen):
ClinGen rates the evidence that AP1S1 causes each of these diseases.
MEDNIK syndrome (autosomal recessive): Definitive.
Homologues: Orthologues: chimpanzee AP1S1 (100% identical), dog AP1S1 (100% identical), macaque AP1S1 (100% identical), mouse Ap1s1 (100% identical), pig AP1S1 (99% identical), rat Ap1s1 (92% identical), guinea pig AP1S1 (91% identical), tropical clawed frog ap1s1 (88% identical), Drosophila melanogaster AP-1sigma (75% identical), Caenorhabditis elegans aps-1 (74% identical), zebrafish AP1S1 (49% identical). Paralogues in human: AP1S2 (86% identical), AP1S3 (67% identical), AP2S1 (41% identical), AP3S1 (38% identical), AP3S2 (37% identical), AP4S1 (32% identical).
Diseases named in the same sentence as AP1S1 in open-access papers:
AP1S1 is named in the same sentence as 31 diseases in open-access papers, as found by Europe PMC text mining. Sharing a sentence is not in itself a finding about the gene and the disease. The quoted sentences say what the papers report.
MEDNIK syndrome (13 papers, 2008 to 2025). "MEDNIK syndrome is a multisystem disorder caused by a mutation in AP1S1, leading to copper absorption or transport dysfunction." (PMID 40901618, 2025). "To date, 23 mutations in AP1S1 have been identified, and five mutation sites are reportedly associated with the pathogenesis or possible pathogenesis of MEDNIK syndrome." (PMID 40901618, 2025). "We report a neonate of Italian origin with MEDNIK syndrome carrying a new homozygous AP1S1 premature stop codon variant, presenting with congenital severe enteropathy and feeding-related non-motor seizures as the early manifestations of the disease." (PMID 41517358, 2025). "We report an Italian native newborn girl with MEDNIK syndrome due to a new AP1S1 variant, presenting with feeding-triggered seizure clusters, which constituted a pivotal undescribed onset symptom." (PMID 41517358, 2025). "We present the first case of Italian origin affected by MEDNIK syndrome carrying a new homozygous AP1S1 stop variant, presenting with congenital severe enteropathy and feeding-related seizures, thus representing an early, singular manifestation of the disease." (PMID 41517358, 2025). "Altogether, we revise the characterization of the disorders associated with AP1S1 gene variants and provide novel insights into the molecular pathogenesis of MEDNIK syndrome." (PMID 39269494, 2024). "MEDNIK syndrome, also known as “syndrome de Kamouraska” (syndrome from Kamouraska), is a genetic disorder that is caused by mutations in adaptor related protein complex 1 subunit sigma 1 (AP1S1) and beta 1 (AP1B1) genes." (PMID 32306098, 2020). "MEDNIK syndrome (OMIM 609313) is caused by mutations in the AP1S1 gene (OMIM 603531) located on chromosome 7q22.1." (PMID 31835360, 2019). "In this study we present a novel splice mutation in human AP1S1, a ubiquitously-expressed gene encoding the small subunit σ1A of AP-1, in four families with MEDNIK syndrome from the Quebec population." (PMID 19057675, 2008). "Overall, our results confirm that mutation of the AP1S1 gene causes MEDNIK syndrome and suggest a critical implication for the AP1S1 gene in development of the skin and spinal cord." (PMID 19057675, 2008). "AP1S1 has been reported to be associated with MEDNIK syndrome progression." (PMID 40901618, 2025). "MEDNIK syndrome (Mental Retardation, Enteropathy, Deafness, Neuropathy, Ichthyosis and Keratodermia) is a hyper-rare autosomal recessive disease with multisystemic involvement, caused by biallelic variants in the AP1S1 gene." (PMID 41517358, 2025). "MEDNIK syndrome (Mental Retardation, Enteropathy, Deafness, Neuropathy, Ichthyosis and Keratodermia) is a severe hyper-rare condition resulting from the biallelic variants in the AP1S1 gene, implicated in intracellular trafficking and copper homeostasis." (PMID 41517358, 2025). "Indeed, mutations in the associated AP1S1 (Adaptor Related Protein Complex 1 Subunit Sigma 1) gene can impact copper metabolism, contributing to MEDNIK syndrome." (PMID 39000354, 2024). "MEDNIK syndrome is a rare autosomal recessive disease characterized by mental retardation, enteropathy, deafness, peripheral neuropathy, ichthyosis, and keratoderma, and caused by variants in the adaptor-related protein complex 1 subunit sigma 1 (AP1S1) gene." (PMID 39269494, 2024). "Mutations in ubiquitously-expressed genes encoding subunits AP1B1 and AP1S1 cause MEDNIK syndrome." (PMID 32306098, 2020). "Since clinical manifestations of CEDNIK show striking similarities to the MEDNIK syndrome described here, we hypothesized that a mutation in AP1S1, a functionally related gene mapping to the candidate interval, may cause the disease." (PMID 19057675, 2008). "The MEDNIK syndrome (an acronym for mental retardation, enteropathy, deafness, neuropathy, ichthyosis, keratodermia), characterized by overlapping symptoms of Wilson and Menkes disease, is caused by a pathogenic variant in the AP1S1 gene that encodes for the σ1A subunit of AP-1." (PMID 38032054, 2024).
MEDNIK syndrome (continued). "In AP1S1-MEDNIK syndrome, the copper homeostasis perturbation is sustained by multiple mechanisms, and its relation to epileptogenesis is yet to be clarified." (PMID 41517358, 2025). "Despite the paucity of cases, for greater phenotypic clarity, in this paper we will review patients with AP1S1-related MEDNIK syndrome only." (PMID 41517358, 2025). "To date, only 18 patients with AP1S1-related MEDNIK syndrome have been reported overall, with a high early lethality." (PMID 41517358, 2025). "We also reviewed the literature focusing on clinical manifestations (especially neurological), brain neuroimaging and the symptom evolution of patients with AP1S1-related MEDNIK syndrome and discuss possible future therapeutic attempts." (PMID 41517358, 2025). "Based on the literature review, we evaluate an overall mortality rate (MR) for AP1S1-related MEDNIK syndrome of 58% (11/19)." (PMID 41517358, 2025). "We reviewed the literature on AP1S1-related MEDNIK syndrome, focusing on neurological features, clinical, molecular, biochemical and neuroradiological hallmarks, therapeutic attempts and disease course." (PMID 41517358, 2025). "AP1S1 (Adaptor Related Protein Complex 1 Subunit Sigma 1): MEDNIK syndrome (Mental retardation, enteropathy, deafness, peripheral neuropathy, ichthyosis, and keratoderma)." (PMID 31031802, 2019). "Together, our results confirm AP1S1 as the gene responsible for MEDNIK syndrome and demonstrate a critical role of AP1S1 in the development of the skin and the spinal cord." (PMID 19057675, 2008). "Together, these results confirm AP1S1 as the gene responsible for MEDNIK syndrome and demonstrate a critical role of AP1S1 in development of the skin and spinal cord." (PMID 19057675, 2008). "To date, only 18 individuals with AP1S1-MEDNIK syndrome have been reported; thus, it must be considered a hyper-rare syndrome, according to Smith’s classification." (PMID 41517358, 2025). "He appears to be the only patient with AP1S1-related MEDNIK syndrome who did not present with this symptom at onset, unlike his affected sister." (PMID 41517358, 2025). "The only difference between the symptoms of AP1B1-related KIDAR and AP1S1-related MEDNIK syndromes is the presence of ophthalmological problems, such as keratitis and corneal scarring, in KIDAR patients, which have not been reported in MEDNIK patients." (PMID 39269494, 2024).
enteropathy (11 papers, 2013 to 2025). "Biallelic mutations of the AP1S1 gene encoding σ1A cause an autosomal recessive multisystem disorder characterized by mental retardation, enteropathy and peripheral neuropathy, named MEDNIK-syndrome." (PMID 37108275, 2023). "We add AP1S1 to the list of congenital diarrhea genes, and show here that an epithelial barrier defect underlies the AP1S1-associated enteropathy." (PMID 32306098, 2020). "AP1S1 mutations cause MEDNIK (mental retardation, enteropathy, deafness, peripheral neuropathy, ichthyosis, and keratoderma) syndrome; AP1S2 mutations are responsible for some forms of X-linked mental retardation; and AP1S3 mutations increase susceptibility to pustular psoriasis." (PMID 37108275, 2023). "In humans, disrupted of AP1S1 has been shown in association with MEDNIK (mental retardation, enteropathy, deafness, neuropathy, ichthyosis, keratodermia) syndrome." (PMID 35464448, 2022). "Mutations in AP1S1, one of the three σ1 subunit genes in humans, results in MEDNIK (mental retardation, enteropathy, deafness, neuropathy, ichthyosis and keratodermia) syndrome." (PMID 23593334, 2013). "In AP1S1-related enteropathy, the disrupted intestinal epithelial barrier might result in increased intestinal ion and macromolecule loss thus explaining the observed secretory diarrhea." (PMID 32306098, 2020). "AP1S1, a clathrin-related protein involved in membrane trafficking and endocytosis, as well as the causal gene for MENDIK (mental retardation, enteropathy, deafness, neuropathy, ichthyosis and keratoderma) syndrome, was differentially expressed in the PFC of chronic alcoholics." (PMID 26381263, 2015).
glioblastoma (3 papers, 2021 to 2024). The most malignant astrocytic tumor (WHO grade IV). "AP1S1, a part of the adaptor protein complex involved in clathrin-mediated endocytosis, is highly expressed in breast cancer and glioblastoma and is associated with poor prognosis." (PMID 39744132, 2024). "In this study, the results showed that CTSD and IER3 were predominantly expressed in myeloid cells, high expression of AP1S1 was shown in glioblastoma cells, and YWHAG was mainly expressed in glioblastoma cells, oligodendrocytes, and myeloid cells." (PMID 35892430, 2022). "CTSD expression was highest in myeloid cells, high expression of AP1S1 was shown in glioblastoma cells, and YWHAG was mainly expressed in glioblastoma cells, oligodendrocytes, and myeloid cells, and IER3 was predominantly expressed in myeloid cells." (PMID 35892430, 2022). "On the other hand, a recent study using bioinformatics have shown that AP1S1 expression is related to glioblastoma multiforme (GBM) pathogenesis and is hypo-methylated and upregulated in acute myeloid leukemia (AML) indicating that its upregulation might have pathological effects in cancer." (PMID 34565296, 2021).
breast carcinoma (2 papers, 2024). "We examined this issue by reducing the prevalence of breast cancer samples (i.e., we only used a half number of breast cancer patients, including 606/1212 randomly selected patients), and we identified a new signature including 7 genes CDK1, AP1S1, CASP3, MAP1LC3A, SNCA, MAPT, and GSK3B." (PMID 38642129, 2024).
congenital enteropathy (2 papers, 2020 to 2025). "Only 18 affected individuals (seven AP1S1 pathogenic variants overall) have been reported to date, with a high early lethality due to life-threatening congenital enteropathy." (PMID 41517358, 2025). "In all but one AP1S1-related MEDNIK reported case, severe congenital enteropathy represented the first symptom, characterized by watery stool, sometimes with a transient blood component, often causing life-threatening dehydration and requiring admission to the NICU." (PMID 41517358, 2025).
copper metabolism disorder (2 papers, 2024 to 2025). "Mutations in AP1S1 can result in abnormal trafficking of copper transporters mediated by adaptor protein complex 1 (AP-1), abnormal intracellular transport of copper pumps, secondary deficiency of copper-dependent enzymes and copper transport disorders." (PMID 40901618, 2025).
lung carcinoma (2 papers, 2026). "To validate this interaction, we performed dual‐luciferase reporter assays demonstrating that lung cancer–derived exosomal miR‐let‐7b‐5p regulates AP1S1 expression through specific binding to its 3 ′UTR region (nucleotide sequence: AGGCUGGA)." (PMID 41551936, 2026). "To further demonstrate the interaction between AP1S1 and miR‐let‐7b‐5p, we overexpressed AP1S1 in macrophages and found that upon cotreatment with the A549‐Exo‐miR‐let‐7b‐5p mimic, AP1S1‐OE significantly counteracted the tumor‐suppressive effects of lung cancer exosomal miR‐let‐7b‐5p." (PMID 41551936, 2026). "A systematic multi-omics analysis was conducted for the eight AP-1 adaptor complex genes (AP1AR, AP1B1, AP1G1, AP1G2, AP1M1, AP1M2, AP1S1, and AP1S3) to characterize their roles in lung cancer." (PMID 41438582, 2026). "Among these, AP1S1 and TNFRSF11A exhibited significantly higher expression in lung cancer tissues than in normal tissues." (PMID 41551936, 2026).
cholestasis (1 paper, 2021). Impairment of the bile flow caused by obstruction within the liver, or outside the liver in the bile duct system. "Alternatively, the loss of AP1S1 could lead to cholestasis via its effect on cellular copper levels." (PMID 33557414, 2021). "We envision two mechanisms via which AP1S1 variants may cause cholestasis." (PMID 33557414, 2021). "Causality between AP1S1 variants and cholestasis has thus far not been demonstrated in cellular or animal model systems." (PMID 33557414, 2021).
cyst (1 paper, 2020). A sac-like closed membranous structure that may be empty or contain fluid or amorphous material. "We observed decreased TEER, increased epithelial dextran permeability and an abnormal cyst formation in 3D cultures of CaCo2 cells devoid of AP1S1." (PMID 32306098, 2020). "Although overall 2D monolayer polarity seemed unaffected, cyst formation and polarity were abnormal in 3D cultures of CaCo2 cells devoid of AP1S1 or expressing the AP1S1 missense mutants." (PMID 32306098, 2020).
lymph node metastasis (1 paper, 2025). "Patients with higher AP1S1 expression have higher estrogen receptor gene expression, increased risk of distant metastasis and lymph node metastasis, and worse overall survival rates." (PMID 39869563, 2025).
tumor (5 papers, 2024 to 2026). "Recent studies have demonstrated abnormal AP1S1 expression in multiple malignancies, which is closely associated with tumorigenesis, tumor progression, and immune escape." (PMID 41551936, 2026). "Collectively, these findings demonstrated that exosomal miR‐let‐7b‐5p derived from A549 cells inhibits AP1S1 expression, thereby modulating M2 polarization of TAMs to suppress tumor invasion and metastasis." (PMID 41551936, 2026). "In‐depth investigation of AP1S1′s mechanistic role in tumor immune escape will not only advance our understanding of the molecular pathways underlying immune evasion but will also identify novel therapeutic targets for immunotherapy." (PMID 41551936, 2026). "Pathological stage-specific analyses revealed progressive upregulation of AP1AR and AP1S3 with advancing tumor stage, whereas AP1S1 expression remained relatively stable." (PMID 41438582, 2026). "Studies have demonstrated that AP1S1 promotes tumor growth, invasion, and metastasis by regulating the function of TAMs." (PMID 41551936, 2026). "AP1S1 not only promotes tumor development through modulation of the activities of the cancer cells but also influences immune escape by regulating immune cells (e.g., macrophages, T cells, and dendritic cells) within the tumor microenvironment." (PMID 41551936, 2026). "Furthermore, AP1S1 influences tumor immune escape by regulating T‐cell functionality." (PMID 41551936, 2026). "Patients whose tumour had high expression of MAP1LC3A, SNCA, and MAPT and low expression of CDK1, AP1S1, CASP3, TMPRSS6, and GSK3B inferred better overall survival than all other patients." (PMID 38642129, 2024). "AP1S1 showed enrichment for IL6-JAK-STAT3 and TNFα-NFκB signaling, as well as apoptosis and G2/M checkpoint pathways, suggesting involvement in both metabolic regulation and tumor-immune interactions." (PMID 41438582, 2026).
cancer (3 papers, 2024 to 2026). A tumor composed of atypical neoplastic, often pleomorphic cells that invade other tissues. "AP1S1, a key regulator of intracellular vesicular transport, plays a critical role in cancer pathogenesis." (PMID 41551936, 2026). "MAP1LC3A, AQP1, and AP1S1 were consistently amplified across cancer types whilst XAF1, CASP3, and SNCA exhibited copy deletions." (PMID 38642129, 2024). "However, AP1S1 is a key component of cellular trafficking and receptor regulation, controlling the availability of surface molecules like growth factor receptors and extracellular matrix elements, reducing immunogenicity in cancer cells." (PMID 40430005, 2025).
genetic disorder (3 papers, 2020 to 2025). "IDEDNIK syndrome is an extremely rare neurocutaneous genetic disorder resulting from pathogenic variants in AP1S1 or AP1B1, which encode subunits of the AP-1 complex." (PMID 41404470, 2025).
AP1S1 also shares sentences with these, for which no sentence is quoted: ichthyosis (10 papers); deafness (9); neuropathy (7); mental retardation (5); peripheral neuropathy (4); acute myeloid leukemia (1); autosomal recessive disease (1); Huppke-Brendel syndrome (1); keratitis (1); liver diseases (1); Menkes disease (1); movement disorder (1); neurocutaneous syndrome (1); progressive familial intrahepatic cholestasis type 3 (1); pustular psoriasis (1); Seizure (1); skin disorder (1); Wilson disease (1).